EGFR (epidermal growth factor receptor)
Diseases named in the same sentence as EGFR in open-access papers (continued):
Sharing a sentence is not in itself a finding about the gene and the disease.
breast carcinoma (continued). "Levels of TGF alpha and beta and EGFR mRNA were analysed in relationship to the relapse-free and overall survival of patients with breast cancer, but none was found to predict significantly the outcome in these patients." (PMID 2331446, 1990). "However, the exact mechanism of the interaction between EGFR and ER on the prognosis of patients with ER+ breast cancer has not been elucidated." (PMID 40422206, 2025). "Conversely, in the MCF-7 cells, the marked decrease observed in all experimental settings may stem from functional crosstalk between the EGFR and IGFR pathways, implying that their interplay could be vital for governing the cellular responses in ERα-positive breast cancer." (PMID 40867236, 2025). "Both compounds inhibited breast cancer cell growth and induced apoptosis and there was a concordance between the effects of NR4A1 and NR4A2 knockdown and effects of DIM-3,5 analogs in MDA-MB-231 cells and on several NR4A-regulated genes including EGFR, β1-integrin, bcl-2 and c-Myc." (PMID 40313760, 2025). "However, the mechanism of the interaction between ER and EGFR in ER+ breast cancer has not been fully elucidated." (PMID 40422206, 2025). "Both compounds inhibited breast cancer cell growth and induced apoptosis and there was a concordance between the effects of NR4A1 and NR4A2 knockdown and effects of DIM-3,5 analogs in TNBC cells and on several NR4A-regulated genes including EGFR, β1-integrin, bcl-2 and c-Myc." (PMID 41184246, 2025). "Furthermore, KEGG pathway enrichment analysis revealed that CSC marker genes were significantly enriched in pathways related to breast cancer, PI3K-Akt signaling, EGFR tyrosine kinase inhibitor resistance, HIF-1 signaling, PD-L1/PD-1 checkpoint regulation, and ErbB signaling." (PMID 41381440, 2025). "Receptor tyrosine kinases (RTKs), such as epidermal growth factor receptor (EGFR) and the insulin-like growth factor I receptor (IGF-IR), are critical cell growth and survival regulators, with their dysregulation closely related to therapy resistance in breast cancer." (PMID 40943584, 2025). "Because EGFR may have a biological role in non-HER2-positive breast cancer, patients without HER2 amplification or overexpression were enrolled in this study." (PMID 40777112, 2025). "Moreover, E2/ERα‐66 and its crosstalk with EGFR signaling pathways induces the upregulation of syndecan‐2, a transmembrane heparan sulfate proteoglycan (HSPG) that is mainly involved in the angiogenesis and the EMT process in ERα+ breast cancer cells." (PMID 39285617, 2025). "In breast cancer, the Grp94 N62Q mutant, which fails to undergo glycosylation, exhibits reduced epichaperome formation, diminished plasma membrane localization, and attenuated EGFR signaling compared to N217A mutant, which retain EGFR signaling." (PMID 41226319, 2025). "Furthermore, when combined with erlotinib, an epidermal growth factor receptor (EGFR) inhibitor, EPZ015666 exhibits additive anticancer effects on MDA-MB-468, BT20, and HCC70 breast cancer cell lines, enhancing the efficacy of either treatment compared to when they were used alone." (PMID 39826691, 2025). "Pivotal examples in this direction are the Michael acceptor-containing inhibitors of EGFR, which react with cysteine residue (Cys797) and neratinib, which potently inhibits HER2 by covalently binding Cys805, approved by the FDA for treatment of HER2+ breast cancer in 2017." (PMID 39962052, 2025). "The epidermal growth factor receptor (EGFR) plays a pivotal role in the development and progression of solid tumors, making it a crucial therapeutic target in various cancer types, including non-small-cell lung carcinoma (NSCLC), breast cancer, gastroesophageal cancer and colorectal cancer." (PMID 39791742, 2025). "Alternatively, YTHDF3 can promote brain metastasis and growth of breast cancer (BC) cells by preferentially translating m6A-rich transcripts such as ST6GALNAC5 and EGFR." (PMID 41446042, 2025).
breast carcinoma (continued). "Whereas, 11.8% of human breast cancer samples exhibited high expression of EGFR (3 +) and 25.4% of human breast cancer samples exhibited low expression of EGFR (1 + and 2 +), and 62.9% of human breast cancer samples did not express EGFR protein (IHC score 0)." (PMID 38982548, 2024). "However, the staining intensity and percentage of EGFR were much weaker in breast cancer samples which were therefore not used for the following analysis." (PMID 39664199, 2024). "DepMap portal plots using publicly available data derived from human breast cancer cell lines and Gepia2 plots using publicly available tumor samples from patients with breast cancer demonstrated that TNBC subtypes show high expression levels of PTK2 (FAK), EGFR, ITGA5, ITGB1, and STAT3." (PMID 38315147, 2024). "SUSD2 expression had negative effects on the prognosis of EGFR+ HER2+ breast cancer patients." (PMID 39791720, 2024). "In vitro studies showed that resistance to EGFR and HER2 inhibitors is, in part, attributed to cytoprotective autophagy, and that inhibiting this process with genetic or pharmacological inhibitors, such as hydroxychloroquine (HCQ), promotes the sensitization of breast cancer cells to treatments." (PMID 39861690, 2024). "Moreover, as the ESMA CAR-interacting endogenous receptors are also expressed on NK cells, their applicability in a CAR NK cell setting should be evaluated, especially considering recent promising in vivo studies of EGFR-directed CAR NK cells against glioblastoma and breast cancer brain metastasis." (PMID 38203786, 2024). "Notably, however, we did not observe any associations with other traits for SFTPB, EGFR, and GAS1, which were associated with a lower risk of lung adenocarcinoma and a higher risk of breast cancer overall and triple-negative breast cancer, respectively." (PMID 38684708, 2024). "The combinatorial treatment with pharmacological inhibitors of EGFR such as gefitinib, erlotinib, and PI3K/AKT pathway has exhibited a synergistic anti‐tumorigenic potential in treating basal subtypes of TNBCs, resulting in reduced metastasis of breast cancer cells." (PMID 38522013, 2024). "However, there is limited information available about its molecular characteristics To the best of our knowledge, no study has reported on the status of VEGF and EGFR expression in Ethiopian female breast cancer." (PMID 39405290, 2024). "In addition to the downregulation of Src, dasatinib was shown to exhibit its effect on BC cell lines through decreasing the phosphorylation of EGFR, as dasatinib was able to induce apoptosis in breast cancer cells (MDA-MB-468, SKBR3, MDA-MB-453, and MDA-MB-231) overexpressing EGFR, HER-2, and HER-3." (PMID 38892472, 2024). "Therefore, in the current study we treated an EGFR/HER2-positive, hormone-independent AI-resistant breast cancer cell line with glyceollin + lapatinib to explore whether a more aggressive breast cancer subtype would be sensitive to combination therapy." (PMID 37049472, 2023). "So, acquired resistance to hormone therapy and overexpression of EGFR/HER2 and activation of EGFR/HER2/MAPK pathway may counterbalance the mTOR activation by PI3K/AKT providing breast cancer cells with potent oncogenic signaling and high levels of cytoprotective autophagy." (PMID 37575061, 2023). "Using an in vitro generated HER2-overexpressed EGFR+ cell line model, this study found that several cytokines, such as CCL2, were increased by HER2 overexpression, leading to a pro-tumoral microenvironment through the CCL2-mediated trafficking of TAMs in breast cancer." (PMID 36674955, 2023). "In addition, molecular interactions between MET and ERBB receptor family signaling pathways may lead to resistance of breast cancer to HER2- and EGFR-targeted therapies, implying that MET is promising for the development of oncodriver-targeted therapies." (PMID 36900322, 2023). "MDA-MB-453 breast cancer cells do not express significant amounts of EGFR and HER2." (PMID 37138747, 2023).
breast carcinoma (continued). "Additionally, a recent study revealed that syringin exerts anti-breast cancer effects through the PI3K-AKT and EGFR-RAS-RAF pathways in MDA-MB-231 and MCF-7 cells in in a culture medium with a high sugar and serum content supplemented with 12% fetal bovine serum (FBS)." (PMID 38068607, 2023). "TKIs combined with macromolecular targeted drugs and chemotherapy may be the main treatment method in the neoadjuvant phase for HER2-positive breast cancer patients in the future, and HER2-positive breast cancer patients with EGFR-positive may benefit more from the use of pyrotinib." (PMID 38114991, 2023). "In the transgenic mouse model whey acidic protein-transforming growth factor α (WAP-TGFα), which develops EGFR-dependent mammary carcinomas, 1/3 of animals showed partial regression, 1/3 no progression and 1/3 demonstrated a complete regression with no observable tumor upon necropsy." (PMID 37720348, 2023). "Various ongoing trials are also following this concept, and patients with ERlo breast cancer are being included in trials evaluating innovative therapies such as PARP inhibitors in combination with durvalumab (NCT 0359594369), the MEK inhibitor selumetinib (NCT01313039), and EGFR inhibitors." (PMID 36506043, 2022). "The recent finding that GBP-1 can be unregulated in breast cancer cell lines by epidermal growth factor receptor (EGFR) signaling might provide clues on why GBP-1 is not protective when all types of breast cancers are considered as a group." (PMID 35681772, 2022). "RQCD1 is frequently upregulated and miR-361-5p frequently downregulated in breast cancer, which was confirmed in TNBC in this study, although this study stopped short of establishing a direct mechanistic link between RQCD1 regulation by miR-361-5p and EGFR-AKT axis regulation." (PMID 35203574, 2022). "Researchers had proved that miR-1296-5p could function as an inhibitor in gastric cancer by targeting cyclin-dependent kinase 6 and epidermal growth factor receptor, ERBB2-positive breast cancer by downregulating ERBB2, in osteosarcoma through repressing notch receptor 2 expression." (PMID 35287543, 2022). "Interestingly, one study has shown that gallic acid, the polyphenol monomer that is found in gallotannin, may inhibit EGFR signalling and MMP-9 activation in breast cancer cells." (PMID 36497413, 2022). "In addition to NSCLC and EGFR TKIs, FAK inhibitors have also been shown to synergize with other therapeutics, including chemotherapeutic drugs in pancreatic ductal adenocarcinoma and breast cancer, and RAF/MEK inhibitors in multiple RAS-driven solid cancers." (PMID 35884490, 2022). "Immunohistochemistry of 45 patients of breast cancer showed that high levels of HIF1α were positively correlated with increased microvascular density (a measure of angiogenesis) (P=0.023) and with expression of angiogenic growth factors bFGF and PDGF-BB and receptor EGFR." (PMID 36226050, 2022). "In breast cancer, disintegrin and metalloproteinase domain-containing protein 12 (ADAM12) is one of the members of MMP family, which its overexpression could increase angiogenesis through epidermal growth factor receptor (EGFR)/STAT3/AKT in BC." (PMID 35499045, 2022). "Interestingly, among the fourteen breast cancer cell lines, these four cell lines alone did not express EGFR or were insensitive to EGF activation, suggesting a specific role for this receptor." (PMID 36380366, 2022). "The individual expression of the constitutively active mutants, Myc-tagged CDC42 (Myc-CDC42(F28L)), Myc-CDC42b(F28L), or the carboxyl terminally V5-tagged ACK (ACK-V5) did not affect the expression of either mTOR or the EGFR in MDA-MB-231 breast cancer cells (lanes 1–4, columns 1–4)." (PMID 36206843, 2022).
breast carcinoma (continued). "In breast cancer models, the EGFR inhibitor erlotinib displayed synergy with THZ1 and with the dual cdc7/CDK9 inhibitor PHA-767491, with more lines of evidence suggesting CDK7 and CDK9 inhibitors could sensitise resistant cancer cells to EGFR-targeted therapy." (PMID 35568739, 2022). "Furthermore, in breast cancer, EGCG inhibits tumor invasion and angiogenesis by suppressing VEGF expression, as well as inhibiting epidermal growth factor receptor (EGFR) and ERK1/2 phosphorylation levels, which also supports the use of HSP70 inhibitors as radiosensitizers for tumors." (PMID 36036010, 2022). "A number of previous findings have inferred indirectly that EGFR may form heterocomplexes with other RTKs, and recent evidence shows that HER2 inhibitor lapatinib induces HER2/HER3 heterocomplex formation in breast cancer cells." (PMID 35612280, 2022). "Therefore, the crosstalk of AR, EGFR, and BRCA1 may affect the significance of AR in breast cancers, especially in TNBC." (PMID 35053220, 2022). "However, the paracrine effects on breast cancer cells of EGFR-regulated miRNAs in MSCs have not been fully explored." (PMID 35406622, 2022). "EGFR and BRCA1 may also affect the function of AR in breast cancers." (PMID 35053220, 2022). "Thus, dual targeting of EGFR/HER2 was found to be more effective rather than only EGFR inhibition for the treatment of breast cancer." (PMID 36678540, 2022). "The homogeneity of these results in breast primary cancer cells was unanticipated, given our previous experiments using cancer cell lines, and we did not expect that all cells from mammary tumours would exhibit aerotaxis, nor did we expect it to be EGFR-dependent in all cases." (PMID 36380366, 2022). "In breast cancer cells, SGLT1 overexpression drives glucose uptake and lactic acid secretion, which promotes macrophage polarization to M2-like TAMs that then activate the EGFR/PI3K/Akt/SGLT1 signaling pathway in the tumor cells to induce resistance to tamoxifen." (PMID 35646668, 2022). "Two cell lines, the human breast cancer cell line (MDA-MB-468) and human glioblastoma cell line (U87 MG), were used since they comprised two cell types with different levels of expression of two membrane receptors, αvβ3 integrin and epidermal growth factor receptor (EGFR)." (PMID 34830084, 2021). "Although c-myc regulation of EGFR/STAT5 signaling has not yet been characterized in melanoma, in breast cancer cell lines expressing the estradiol receptor, EGFR and c-Src kinase function are correlated with estradiol-induced cyclin D1 and c-myc gene transcription." (PMID 34067095, 2021). "ErbB1 (EGFR) and ErbB2 (HER2/Neu) drive oncogenesis in many human malignancies; ErbB2 overexpression, due to gene amplification and/or increased transcription, drives oncogenesis in up to a quarter of human breast cancer patients and specifies poor overall patient survival." (PMID 34439093, 2021). "Therefore, we speculated whether EVs-miR-182-5p can regulate activation of the EGFR/AKT signaling pathway through inhibition of CMTM7, thus promoting breast cancer angiogenesis." (PMID 34294040, 2021). "Hypoxic human breast cancer cells (2 million) were injected into female nu/nu mice for tumor inoculation, followed by treatment with paclitaxel- and lonidamine-loaded EGFR-targeted NPs, paclitaxel- and lonidamine-loaded non-targeted NPs, and paclitaxel and ionidamine solution." (PMID 33530291, 2021). "We, therefore, tested whether the CDK inhibitor, dinaciclib, could block MCL-1 in preclinical HER2-amplified breast cancer models and therefore sensitize these cancers to dual HER2/EGFR inhibitors neratinib and lapatinib, as well as to the novel selective HER2 inhibitor tucatinib." (PMID 33589591, 2021).
breast carcinoma (continued). "For example, Dox-containing liposomes conjugated with MPEG-DSPE FabV fragments of cetuximab immunoliposomes showed better results for internalization within EGFR overexpressed cancer cells and regression in human breast cancer model, i.e., MDAMB-68 versus non-targeted liposomes." (PMID 33800723, 2021). "Moreover, we found that SHP-1 and EGFR not only were correlated with each other but also predicted the OS of patients with breast cancer, thus highlighting the value of SHP-1 as a novel prognostic biomarker in human breast cancer." (PMID 34591414, 2021). "The EGFR-specific antibodies cetuximab and panitumumab have been widely used in the treatment of EGFR-expressing and KRAS wild-type colorectal cancer; and the HER2-targeting antibody trastuzumab has been successful in improving the outcomes of patients with HER2-expressing breast cancer." (PMID 32646879, 2021). "YES1 gene amplification occurs in some types of cancer and is a key mechanism of resistance to EGFR or HER2 inhibitors, while downregulation of YES1 inhibits cell growth in several malignancies, including colon carcinoma, rhabdomyosarcoma, and basal-like breast cancer." (PMID 33941853, 2021). "Indeed, EGFR and c-Src are expressed and could be activated by EGF, suggesting that the EGFR/c-Src signaling is intact in breast cancer cell lines." (PMID 33407765, 2021). "To test the silencing activity of nanostructures 1/2 towards the endogenous mRNA of EGFR protein, we used human squamous cell carcinoma cells (A431) expressing higher levels of EGF receptor compared to HeLa (human cervical carcinoma) and MCF-7 (human breast cancer) cell lines." (PMID 34064412, 2021). "Our data do not support the published hypothesis of an overexpression-induced mechanism for ligand-independent EGFR homodimerization because EGFR expression in SKBR3 cells is even lower than in normal breast tissue, as is generally the case in human breast cancers." (PMID 34831465, 2021). "Beyond drugs that directly target proteins such as ER, EGFR, HER2, MET, PI3K, AKT, mTOR, and those of the MAPK pathway, anti-apoptotic protein inhibitors (BH3 mimetics) are now being evaluated as new targeted therapies for breast cancer as increased anti-apoptotic protein levels have been reported." (PMID 34359829, 2021). "Although AXL has been shown previously to relay secondary resistance to EGFR and HER targeted therapies in a subset of breast and lung cancers, a marked increase of AXL expression and stability in our small cohort of relapsed breast cancer tumors was unexpected." (PMID 33850249, 2021). "Effective treatments for HER2+ breast cancers include the monoclonal antibody trastuzumab, the antibody–drug conjugate ado-trastuzumab emtansine, and the dual tyrosine kinase inhibitor lapatinib which targets both the HER/neu and the epidermal growth factor receptor (EGFR)." (PMID 33671674, 2021). "Prognosis analysis in the samples without EGFR amplification demonstrated that breast cancer patients with high expression of SEC61G had significantly worse overall survival (OS) and disease-free survival (DFS) than those patients with low expression of SEC61G in TCGA BRCA cohort." (PMID 34039955, 2021). "Given the importance of the V-ATPase in breast cancer, in this paper we characterized the molecular mechanism through which the V1G1 subunit of the pump controls the invasive phenotype of breast cancer cells with a particular focus on the EGFR signaling using the MDA-MB-231 model system." (PMID 33633298, 2021). "For instance, feeding EGFR protein expression into the Human protein atlas database which also accounts for protein expression indicates that EGFR is (a) not prognostic in breast cancer (b) is less frequently detected in the immunohistochemistry samples of breast cancer patients." (PMID 34754042, 2021).